ALK (ALK receptor tyrosine kinase)
Diseases named in the same sentence as ALK in open-access papers (continued):
Sharing a sentence is not in itself a finding about the gene and the disease.
lung adenocarcinoma (continued). "Targeted treatments with tyrosine kinase inhibitors (TKI) have become the first line therapy for patients with advanced lung adenocarcinoma bearing EGFR mutations or ALK rearrangement, thanks to the improved clinical response and tolerability profile of these drugs compared to standard chemotherapy." (PMID 28560038, 2017). "ALK-rearranged lung adenocarcinomas were associated with histologic subtypes." (PMID 27386342, 2016). "Our findings indicate that advanced ALK-positive lung adenocarcinoma was significantly associated with the presence of lymphadenopathy, lymph nodes with extranodal invasion, lymphangitis, and pleural effusion, and that these tumors were less likely to exhibit GGO components." (PMID 27518729, 2016). "Other mutually exclusive genetic alterations, which have been reported to work as driver mutations in lung adenocarcinoma, include translocations of ALK, ROS1, RET, NTKR1, NRG2, ERBB4, and BRAF, and mutations of KRAS, BRAF, ERBB2, NRAS, HRAS, MAP2K1, NF1, and RIT1." (PMID 27005669, 2016). "The identification of therapeutically tractable molecular targets, particularly epidermal growth factor receptor (EGFR) mutation and anaplastic lymphoma kinase (ALK) rearrangement, has led to the dramatic improvement in personalized therapy for lung adenocarcinoma." (PMID 27145277, 2016). "ALK rearrangement is rare in lung adenocarcinoma presenting as nGGOs and is associated with a more advanced stage and larger tumor size, suggesting a distinct origin and an aggressive nature in the progression of lung adenocarcinoma." (PMID 24885886, 2014). "However, only patients with lung adenocarcinoma with EGFR mutations or anaplastic lymphoma kinase (ALK) rearrangements have an FDA-approved therapy available." (PMID 24587185, 2014). "The objectives of this study were to determine the frequency of ALK rearrangements in a large cohort of patients with primary lung adenocarcinoma and to analyze the association of ALK rearrangements with clinicopathological characteristics and clinical outcomes." (PMID 24992725, 2014). "Consequently, tyrosine kinase inhibitors targeting epidermal growth factor receptor (EGFR) and anaplastic lymphoma kinase (ALK) have become the standard treatment for patients with metastatic EGFR‐ or ALK‐mutated lung adenocarcinoma, and these tests are performed in routine practice." (PMID 33960703, 2021). "However, to the best of our knowledge, there is no study in the literature showing whether there is a relationship between intratumoral IGFR1 expression and ALK mutation status in lung adenocarcinomas." (PMID 32876329, 2021). "The aim of the present study was to detect over-expression of ALK protein with the Ventana IHC test and to examine the associations of ALK rearrangement with clinicopathologic characteristics and treatment outcomes in patients with early-stage lung adenocarcinoma." (PMID 29156778, 2017). "In this report, we present a patient case of ALK-rearranged lung adenocarcinoma with SCLC transformation after ALK TKI treatment and subsequently treated successfully with tarlatamab while continuing lorlatinib." (PMID 41584719, 2026). "We present a patient with Anaplastic lymphoma kinase (ALK) fusion lung adenocarcinoma who received sequential treatment with ALK tyrosine kinase inhibitor (TKI) (crizotinib, PFS:32.3 months and then conteltinib, PFS: 29 months)." (PMID 41869647, 2026). "Current targeted therapies for LUSC harboring ALK, ROS1, or EGFR mutations are typically guided by protocols established for lung adenocarcinoma." (PMID 41868215, 2026). "A 63-year-old female underwent radical resection for stage IA lung adenocarcinoma (ALK-positive) and received adjuvant ensartinib." (PMID 42222403, 2026). "We report a case of a 34-year-old female patient who developed aseptic inflammatory abscesses in the back and nephritic inflammatory abscesses induced by crizotinib treatment for ALK-rearranged lung adenocarcinoma." (PMID 42222397, 2026).
lung adenocarcinoma (continued). "We report a novel intergenic anaplastic lymphoma kinase (ALK) fusion identified in a patient with resected stage IIIA lung adenocarcinoma." (PMID 42137140, 2026). "We report a rare case of primary glioblastoma occurring approximately two years after surgery for anaplastic lymphoma kinase (ALK)-positive lung adenocarcinoma." (PMID 42222403, 2026). "Approximately 60% of patients with lung adenocarcinoma harbor driver gene alterations, and about 2%–7% of these cases exhibit anaplastic lymphoma kinase (ALK) fusions." (PMID 41487577, 2025). "This case offers a potential reference for the management of ALK fusion–positive lung adenocarcinoma resistant to ALK tyrosine kinase inhibitors (ALK-TKIs)." (PMID 41487577, 2025). "The establishment of positive and negative controls in immunohistochemistry (IHC) screening for anaplastic lymphoma kinase (ALK) rearrangements is essential in the treatment of lung adenocarcinoma." (PMID 40017673, 2025). "Three-dimensional (3D) spheroid co-cultures comprising ALK-rearranged lung adenocarcinoma cells and CAFs were utilized to model the tumor microenvironment." (PMID 40524253, 2025). "The global real-world study GLASS, which analyzed the efficacy of lorlatinib in 106 ALK-positive advanced lung adenocarcinoma patients, showed an ORR of 62% and a DCR of 88% in patients with brain metastasis." (PMID 40376587, 2025). "Patients with ALK-rearranged lung adenocarcinoma exhibit low response rates to ICIs, potentially due to distinct TIME characteristics." (PMID 40376302, 2025). "This study included 626 lung adenocarcinoma patients, with EGFR mutations found in 58.63% (367/626) and ALK gene rearrangements in 6.23% (39/626) of cases." (PMID 41378298, 2025). "ALK TKIs have been shown to be highly effective in lung adenocarcinomas with ALK-fusions, leading to dramatically improved survival rate." (PMID 40615663, 2025). "We encountered a rare case of ALK-positive lung adenocarcinoma that responded to pembrolizumab monotherapy as the 8th-line treatment." (PMID 40660550, 2025). "This case report describes a stage IV ALK-rearranged lung adenocarcinoma (LUAD) patient who developed KIF5B-RET fusion-mediated resistance to second-line alectinib therapy." (PMID 40599544, 2025). "In NSCLC, ALK aberrations most frequently manifest as gene rearrangements, with the EML4-ALK fusion being the prototypical example, detected in approximately 3–7% of lung adenocarcinomas." (PMID 41614760, 2025). "A 41-year-old woman was diagnosed in the postpartum period with Stage IIIA (cT1cN2M0) ALK fusion gene–positive lung adenocarcinoma." (PMID 41036487, 2025). "In our research, we discovered a rare ALK fusion, TTC7A-ALK, in a patient with advanced lung adenocarcinoma using targeted next-generation sequencing (NGS)." (PMID 40054123, 2025). "We report a case of initially unresectable Stage IIIA ALK-rearranged lung adenocarcinoma that was discovered incidentally during evaluation for a Caesarean section." (PMID 41036487, 2025). "The rearrangement of the ALK gene is one of the common driver genes in lung adenocarcinoma, and the patients benefited significantly from the effects of the targeting of Alectinib and Crizotinib." (PMID 39940064, 2025). "These subgroups were chosen for comparative analysis because ALK and ROS1 fusions are well‐validated fusion genes in lung adenocarcinoma, whereas EGFR mutations are a commonly validated driver gene primarily receiving targeted therapy." (PMID 40751559, 2025). "The EGFR and ALK genes are also the primary gene targets for targeted therapy in lung adenocarcinoma." (PMID 41020204, 2025). "This article reports the case of a long-term surviving patient with EML4/ALK translocated non–small cell adenocarcinoma of the lung in UICC8 stage IVA." (PMID 38960389, 2025).
lung adenocarcinoma (continued). "Anaplastic lymphoma kinase (ALK) is an important driver gene and therapeutic target for lung adenocarcinoma." (PMID 40083024, 2025). "The quantitative and qualitative parameters of three-dimensional CT are closely associated with EGFR gene mutations, ALK gene rearrangements, and prognosis in patients with GGO-associated lung adenocarcinoma." (PMID 41020204, 2025). "In the field of ALK-TKIs for NSCLC, in addition to terms such as “ALK-TKI” and “lung adenocarcinoma,” the prominent keywords are primarily associated with three major research areas: drug resistance mechanisms, circulating tumor DNA, and immunotherapy." (PMID 40894217, 2025). "EGFR and ALK mutations are recognized as critical drivers in the development of NSCLC, especially lung adenocarcinoma, and serve as important targets for clinical therapy." (PMID 41378298, 2025). "Our research has developed a radiomics model to predict brain metastasis (BM) in stage III/IV ALK-positive lung adenocarcinoma patients after detecting the primary tumor." (PMID 40606995, 2025). "In conclusion, we hereby report, for the first time, a case of lung adenocarcinoma harboring a novel ELMOD3-ALK and EML4-ALK double-ALK fusion." (PMID 40297141, 2025). "Molecular profiling for driver mutations such as EGFR, ALK, and ROS1 is essential in advanced lung adenocarcinomas." (PMID 40949067, 2025). "This case demonstrates the efficacy of neoadjuvant alectinib in managing ALK-mutant stage III lung adenocarcinoma, highlighting the potential benefits of targeted therapy in the neoadjuvant setting." (PMID 41293380, 2025). "CT-derived radiomic signatures show promise as a tool for predicting BM within 2 years after detection of primary lung adenocarcinoma detection with ALK+." (PMID 40606995, 2025). "Cox regression analysis was used to identify statistically significant factors for progression-free survival (PFS) in ALK-positive lung adenocarcinoma, with model discrimination evaluated by the concordance index (C-index)." (PMID 40606995, 2025). "In ALK‐rearranged lung adenocarcinoma patients treated with ALK tyrosine kinase inhibitors, squamous lineage plasticity also drives therapy resistance." (PMID 41415713, 2025). "This is the first report of one lung adenocarcinoma patient with a novel ELMOD3-ALK, EML4-ALK double-ALK fusion." (PMID 40297141, 2025). "Herein, we present a patient with lung adenocarcinoma harboring a novel ALK rearrangement who exhibited major pathological response (MPR) following neoadjuvant treatment with alectinib." (PMID 40860868, 2025). "Among the Caucasian population, ALK rearrangements are present in approximately 3%–7% of lung adenocarcinoma cases." (PMID 39810398, 2025). "We present a case of Stage IIIA ALK fusion gene–positive lung adenocarcinoma treated with alectinib followed by salvage surgery resulting in a pCR." (PMID 41036487, 2025). "We conducted a retrospective study of patients with advanced lung adenocarcinoma harboring ALK, ROS1, and RET fusions, comparing them with cohorts harboring EGFR mutations." (PMID 40751559, 2025). "Combined with the contrast-enhanced thoracoabdominal CT, the patient was ultimately diagnosed with lung adenocarcinoma (stage IVB, T4N3M1c) with ALK rearrangement and multiple gene mutations on February 23, 2021." (PMID 40052122, 2025). "Several studies have revealed that TPR can fuse with other kinase domains of oncogenes, including TRK in human papillary thyroid carcinomas, FGER1 in myeloproliferative syndrome, and ALK in lung adenocarcinoma." (PMID 40722683, 2025). "In October 2015, he underwent a wedge resection of the lung using video‐assisted thoracoscopic surgery, which revealed ALK‐rearranged lung adenocarcinoma (pT4N0M0)." (PMID 40542555, 2025). "We herein present a rare case of ALK-positive lung adenocarcinoma that responded to pembrolizumab monotherapy as the 8th-line treatment." (PMID 40660550, 2025).
lung adenocarcinoma (continued). "Common mutation types in lung adenocarcinoma include epidermal growth factor receptor (EGFR), anaplastic lymphoma kinase (ALK) rearranged, and C-ros oncogene 1-receptor tyrosine kinase (ROS1) fusion." (PMID 40134592, 2025). "Ovarian metastasis from anaplastic lymphoma kinase (ALK)-positive lung adenocarcinoma is exceedingly rare." (PMID 41261685, 2025). "ALK kinase inhibitors, such as crizotinib, are now established as the standard first‐line therapy for ALK–rearranged lung adenocarcinoma, offering superior progression‐free survival compared to conventional chemotherapy." (PMID 39810398, 2025). "Many lung adenocarcinomas have an actionable driver mutations involving genes such as epidermal growth factor receptor (EGFR), anaplastic lymphoma kinase (ALK), Kirsten rat sarcoma virus (KRAS), MET, c-ros oncogene 1 (ROS1), HER2, BRAF, RET, and NTRK." (PMID 40006675, 2025). "The advent of the ALK inhibitor, crizotinib, significantly improved the treatment of ALK+ advanced lung adenocarcinoma, demonstrating better outcomes than chemotherapy." (PMID 40606995, 2025). "This study included 626 patients with early-stage lung adenocarcinoma who underwent surgical resection between October 2017 and December 2023.EGFR and ALK mutations were analyzed postoperatively." (PMID 41378298, 2025). "Based on our current knowledge, there have been no previous explorations on the predictive role of CT-based radiomics analysis for brain metastases in patients with ALK-positive lung adenocarcinoma." (PMID 40606995, 2025). "The results revealed that these factors were correlated with ALK gene rearrangement in GGO-related lung adenocarcinoma." (PMID 41020204, 2025). "This study aims to develop and validate a computed tomography (CT)-based radiomics nomogram for predicting brain metastases in lung adenocarcinoma with anaplastic lymphoma kinase positive (ALK+)." (PMID 40606995, 2025). "We report a rare case of ALK fusion–positive lung adenocarcinoma with concurrent high programmed death-ligand 1 (PD-L1) expression and a Bcl-2-like protein 11 (BIM) deletion polymorphism." (PMID 41487577, 2025). "Targeted therapy interventions using tyrosine kinase inhibitors (TKIs) provide encouraging treatment responses in patients with ALK-rearranged lung adenocarcinomas, yet resistance occurs almost inevitably." (PMID 40524253, 2025). "This retrospective study included 66 ALK-positive and 66 ALK-negative patients who underwent surgical resected lung adenocarcinoma." (PMID 40376302, 2025). "Here, we report a case of a 68‐year‐old Korean male with ALK‐positive lung adenocarcinoma who developed CARCs during long‐term therapy." (PMID 40542555, 2025). "In summary, the quantitative and qualitative parameters of three-dimensional CT are related to EGFR and ALK gene rearrangements and prognosis in patients with GGO-associated lung adenocarcinoma." (PMID 41020204, 2025). "The presented combined model based on GPTV3 effectively mined tumor features to predict ALK mutation status and stratify PFS outcomes in patients with lung adenocarcinoma." (PMID 40083024, 2025). "Analysis of primary tumours from multifocal lung adenocarcinomas reported ~5% of EGFR/ALK co-alterations." (PMID 39695132, 2024). "A 60-year-old male patient (PDC case-131) with stage IV lung adenocarcinoma displaying ALK fusion received crizotinib." (PMID 38398169, 2024). "Our patient had a very rare ALK-rearrangement lung adenocarcinoma and received ALK inhibitors and developed SCLC transformation and secondary mutations in the ALK kinase domain with drug resistance." (PMID 38961982, 2024). "The echinoderm microtubule-associated protein-like 4 (EML4)–anaplastic lymphoma kinase (ALK) fusion is a common genetic alteration estimated to exist in ∼5% of lung adenocarcinomas." (PMID 38458397, 2024). "Among ALK fusion mutations that occur in NSCLC, EML4 is the most common gene fusion partner in ALK-rearranged lung adenocarcinoma." (PMID 39911820, 2024).
lung adenocarcinoma (continued). "The research advances our understanding of PD‐L1 expression's genomic context and immunotherapy response in EGFR/ALK wild‐type lung adenocarcinoma." (PMID 38396367, 2024). "Previous study indicated that ALK-positive lung adenocarcinoma patients exhibit distinct clinical characteristics." (PMID 39497711, 2024). "One disease that closely approximates the lineage transitions observed in prostate cancer is EGFR- or ALK-mutant lung adenocarcinoma, where NE transition is a mechanism of escape from EGFR or ALK inhibition." (PMID 39394434, 2024). "Here, we report a 56-year-old lung adenocarcinoma female patient with brain metastasis and dual ALK fusion of LOC399815-ALK and ALK-EML4." (PMID 38241569, 2024). "Due to the availability of effective therapies, all lung adenocarcinomas should be investigated for ALK fusion oncogenicity." (PMID 38605928, 2024). "The most advanced studies focused on the signet ring cell morphology, which was frequently reported in lung adenocarcinomas with ALK-rearrangement, predominantly diagnosed as advanced cancer in young, never-smoker females." (PMID 38256374, 2024). "This study analyzed EGFR/ALK wild‐type lung adenocarcinoma patients to explore correlations between gene/pathway alterations and PD‐L1 TPS." (PMID 38396367, 2024). "In this retrospective study, tumor samples from 359 Chinese EGFR/ALK wild‐type lung adenocarcinoma patients underwent comprehensive evaluations for PD‐L1 expression and NGS‐targeted sequencing." (PMID 38396367, 2024). "A 37-year-old female patient (case NCCLu-089) was diagnosed with stage IV lung adenocarcinoma displaying ALK fusion." (PMID 38398169, 2024). "Approximately 45-50% of Asian patients with lung adenocarcinoma have EGFR mutations and the prevalence of ALK mutations is around 7%." (PMID 39850198, 2024). "Alterations in the anaplastic lymphoma kinase (ALK) gene are one of the most common driver mutations detected among Western and Asian patients with lung adenocarcinoma in 4% of cases." (PMID 39061248, 2024). "To complement the initial findings, we expanded the GSEA-based analysis to identify significantly upregulated or downregulated pathways in ROS1+ lung adenocarcinomas and cell lines in comparison to ALK/RET+ tumor samples." (PMID 39737401, 2024). "High tumor mutational burden correlated significantly with PD‐L1 positivity in patients with EGFR/ALK wild‐type lung adenocarcinoma." (PMID 38396367, 2024). "Herein, we present a case of ALK-positive lung adenocarcinoma in which the patient achieved extended survival after undergoing precise pleural effusion NGS and combined bevacizumab treatment following multiple-line ALK-TKI resistance." (PMID 38978737, 2024). "ALK gene rearrangements have been considered one of most frequently dominant oncogenic drivers in lung adenocarcinoma, and matched TKI drugs are recommended as the standard option due to their significant impacts." (PMID 39267820, 2024). "ALK rearrangements are commonly identified in lung adenocarcinoma; LCNEC with ALK rearrangements is exceedingly rare and often associath-grade pathology, advanced-stage presentation, and poor prognosis." (PMID 39723252, 2024). "This is the first case presenting a rare concomitant ALK double-fusion, namely PLEKHA7-ALK and INPP5D-ALK, in a patient with lung adenocarcinoma, who exhibited favorable sensitivity to alectinib." (PMID 38379102, 2024). "Adenocarcinomas with psammoma bodies are often associated with tyrosine kinase inhibitor-targetable driver mutations in EGFR (69.8%), ALK (13.2%), and ROS1 (1.9%), although the presence of psammoma bodies in ROS1-fused lung adenocarcinomas remains debated." (PMID 39391406, 2024). "This study offers insights into genomic features of Chinese EGFR/ALK wild‐type lung adenocarcinoma patients based on PD‐L1 expression." (PMID 38396367, 2024).